NMRAL2P (NmrA like redox sensor 2, pseudogene )
Synonyms: NMRAL1P1
Gene: Long non-coding RNA gene on chromosome 3 (185,959,734 to 186,012,561, forward strand). Ensembl gene ENSG00000290862.
Diseases named in the same sentence as NMRAL2P in open-access papers:
NMRAL2P is named in the same sentence as 6 diseases in open-access papers, as found by Europe PMC text mining. Sharing a sentence is not in itself a finding about the gene and the disease. The quoted sentences say what the papers report.
colon cancer (3 papers, 2019 to 2025). "NMRAL2P, another pseudogene identified in SFN‐exposed colon cancer cells, is regulated by the Nrf2 pathway and enhances antioxidant activity and carcinogen detoxification." (PMID 40556338, 2025). "Transcriptomic analysis in SFN‐exposed colon cancer cells revealed the non‐coding RNA Loc344887, regulated by Nrf2 and aiding NQO1 activity, identified as NMRAL2P." (PMID 40556338, 2025). "NmrA-like redox sensor 2 pseudogene (NMRAL2P) is the first functional pseudogene that was identified as a direct target of NRF2 and downstream regulator of NRF2-dependent NQO1 activation in sulforaphane (SFN)-treated colon cancer cells." (PMID 33287295, 2020).
heart failure (1 paper, 2023). Inability of the heart to pump blood at an adequate rate to meet tissue metabolic requirements. "Moreover, expression level of NMRA-like protein NMRAL1 pseudogene (NMRAL2P) is significantly decreased in the right ventricle in heart failure, suggesting that NMRAL2P is involved in heart failure." (PMID 37491351, 2023).
cancer (4 papers, 2019 to 2025). A tumor composed of atypical neoplastic, often pleomorphic cells that invade other tissues. "Although its precise function remains to be clarified, potential roles for NMRAL2P as a prognostic factor and/or a therapeutic target for cancer have been reported." (PMID 30737573, 2019). "Only NMRAL2P was substantially expressed in cancer tissues and predicted a poor prognosis." (PMID 37810778, 2023).
tumor (4 papers, 2019 to 2025). "NMRAL2P-oe was transferred into TU177 and AMC-HN-8 cells and the results showed that the overexpression of NMRAL2P enhanced the proliferation, migration, and invasion of tumor cells." (PMID 37810778, 2023). "Compared with the control group, the expression of NMRAL2P increased around 100x in the overexpression group, and compared to the vector, the NMRAL2P overexpression increased the viability, migration, invasion, and proliferation of tumor cells." (PMID 37810778, 2023). "MTS, Transwell, and clone formation assays showed that NMRAL2P overexpression increased the viability, migration, invasion and proliferation of tumor cells, while ENO1 gene knockout partially counteracted this tumor promoting effect." (PMID 37810778, 2023). "Functional recovery assays were carried out to further clarify the role of NMRAL2P and ENO1 in tumor promotion." (PMID 37810778, 2023). "The cytoplasmic portion of NMRAL2P can bind to the ENO1 protein, postpone ENO1’s breakdown, promote glycolysis, and provide extra energy to tumor cells." (PMID 37810778, 2023). "According to data retrieved from TCGA, NMRAL2P exhibits notably lower expression in human CRCs than in normal tissues, suggesting its potential as an emergent tumor suppressor biomarker." (PMID 40556338, 2025). "In the lncRNA group, lncRNA-TOB2P1, LOC100499489, lnc-NMRAL2p, and lnc-NBPF22P were markedly upregulated in tumor tissues, while LINC01093, LOC100130899, LOC200772, and lnc-FENDRR were significantly downregulated in tumor tissues, compared to the adjacent controls." (PMID 31156698, 2019). "In contrast, NMRAL2P and SHH showed significant negative correlations with multiple immune checkpoint genes, indicating that tumors with higher expression of these genes tend to display a “cold tumor” immune microenvironment, which may correspond to a poorer response to immunotherapy." (PMID 41425595, 2025).
head and neck tumors (2 papers, 2023 to 2025). "Only NMRAL2P was highly expressed in head and neck tumors and high expression of the gene was associated with poor prognosis." (PMID 37810778, 2023). "The lncRNA NMRAL2P is linked to oxidative stress regulation in head and neck tumors." (PMID 40556338, 2025). "To reverse-verify the function of NMRAL2P in head and neck tumor cells, we transferred NMRAL2P-ASO into TU177 and AMC-HN-8 cells, respectively, and the relative expression of NMRAL2P in TU177 and AMC-HN-8 was knocked down by more than 40%." (PMID 37810778, 2023). "The overexpression of NMRAL2P led to an increase in lactic acid synthesis, and the downregulation of ENO1 led to a decrease in lactic acid production, indicating that NMRAL2P acts on ENO1 to promote head and neck tumor cells." (PMID 37810778, 2023).
NMRAL2P also shares sentences with these, for which no sentence is quoted: gallbladder cancer (1 paper).